SLC10A3 (solute carrier family 10 member 3)
Description:
The ubiquitous expression and the conservation of the sequence in distant animal species suggest that the gene codes for a protein with housekeeping functions.
Synonyms: DXS253E; P3
Tractability: Antibody: UniProt predicts a signal peptide or a membrane-spanning region.
Gene: Protein-coding gene on chromosome X (154,487,306 to 154,490,690, reverse strand). Ensembl gene ENSG00000126903.
Subcellular location: Membrane
Subcellular location (Human Protein Atlas): Intermediate filaments
Gene Ontology:
Molecular function: bile acid:sodium symporter activity
Biological process: bile acid and bile salt transport
Cellular component: plasma membrane; membrane
Homologues: Orthologues: chimpanzee SLC10A3 (99% identical), dog SLC10A3 (88% identical), pig SLC10A3 (88% identical), macaque UBL4A (88% identical), mouse Slc10a3 (85% identical), rat Slc10a3 (85% identical), guinea pig SLC10A3 (85% identical), rabbit SLC10A3 (81% identical), zebrafish slc10a3 (52% identical), tropical clawed frog slc10a3 (51% identical), Caenorhabditis elegans Y71G10AR.4 (21% identical), Drosophila melanogaster CG9903 (20% identical), and 1 more. Paralogues in human: SLC10A5 (33% identical), SLC10A1 (19% identical), SLC10A4 (19% identical), SLC10A6 (19% identical), SLC10A2 (16% identical).
Diseases named in the same sentence as SLC10A3 in open-access papers:
SLC10A3 is named in the same sentence as 23 diseases in open-access papers, as found by Europe PMC text mining. Sharing a sentence is not in itself a finding about the gene and the disease. The quoted sentences say what the papers report.
breast carcinoma (2 papers, 2015 to 2023). "We found that SLC10A3 is up-regulated in most types of malignant tumors, such as breast cancer, cholangiocarcinoma, esophageal carcinoma, head and neck squamous cell carcinoma, liver cancer, lung cancer, colorectal cancer, gastric cancer." (PMID 37166424, 2023).
colorectal cancer (2 papers, 2023 to 2024). A primary or metastatic malignant neoplasm that affects the colon or rectum. "SLC10A3, a gene upregulated in pan-cancer, lacks full understanding regarding its prognostic implications and association with immune infiltration in colorectal cancer (CRC)." (PMID 38178258, 2024). "Thus, this study aims to elucidate the expression of SLC10A3, immunocorrelation and its significant role in predicting the prognosis of colorectal cancer, ultimately establishing a genetic risk-scoring model." (PMID 38178258, 2024). "Transcriptomic data from TCGA were obtained to compare SLC10A3 expression in both colorectal cancer (CRC) and normal tissues." (PMID 38178258, 2024). "Additionally, although we found an association between SLC10A3 and the immune microenvironment of colorectal cancer, confirmatory experiments were not conducted." (PMID 38178258, 2024). "Nonetheless, there is currently no literature on SLC10A3 in colorectal cancer." (PMID 38178258, 2024).
glioma (2 papers, 2023 to 2024). A benign or malignant brain and spinal cord tumor that arises from glial cells (astrocytes, oligodendrocytes, ependymal cells). "Upregulation of SLC10A3 mRNA is statistically related with unfavorable survival outcomes and immune infiltration among low-grade gliomas." (PMID 38178258, 2024). "Thereby, our next research will focus on the exact biological mechanism of SLC10A3 in glioma." (PMID 37166424, 2023).
liver cancer (2 papers, 2023 to 2024). An epithelial or non-epithelial malignant neoplasm that arises from the liver. "Specifically, SLC10A3 plays a critical role in regulating the immune response in liver cancer, related with stromal CD4 T cells, CD20 B cells, and macrophage." (PMID 38178258, 2024). "Recent studies suggest that SLC10A3 may influence chemotherapy resistance and serve as a promising immune biomarker in liver cancer." (PMID 38178258, 2024). "Moreover, the expression of SLC10A3 protein is correlated with stromal CD4 T cells, CD20 B cells, macrophages, PDCD1 (PD-1) and CD274 (PD-L1) expression, indicating a potential regulatory role in liver cancer immunotherapy." (PMID 38178258, 2024).
cognitive decline (1 paper, 2025). "By contrast, greater HDAC8 and SLC10A3 expression was associated with greater tau tangle burden and faster cognitive decline, respectively, in females only." (PMID 40166028, 2025). "When focusing on X-linked genes, sex significantly moderated MCF2, HDAC8, SLC10A3, and FTX on tau tangle burden or cognitive decline in the DLPFC." (PMID 40166028, 2025). "Higher SLC10A3 expression was associated with faster cognitive decline in females (β=−0.02, pFDR=0.04), but not in males (β = 0.02, pFDR=0.24)." (PMID 40166028, 2025).
colon cancer (1 paper, 2024). "We evaluated the accuracy of a colon cancer risk prediction model based on SLC10A3 using ROC curve analysis and found that the sensitivity was greater than the specificity, with an area under curve (AUC) of 0.745." (PMID 38178258, 2024).
colorectal adenocarcinoma (1 paper, 2024). The most common type of colorectal carcinoma. "Therefore, this study evaluates the transcriptional profiles and potential prognostic value of the SLC10A3 by systematical bioinformatics analysis and provides a novel role of SLC10A3 in the prognostic value and immune microenvironment in colorectal adenocarcinoma." (PMID 38178258, 2024). "However, whether SLC10A3 plays a similar role in colorectal adenocarcinoma remains unknown." (PMID 38178258, 2024).
Pan (1 paper, 2023). "Pan-cancer analysis revealed that up-regulation of SLC10A3 is not only a risk factor for worse overall survival among LGGs, but also a risk factor for inferior progression-free survival among LGGs." (PMID 37166424, 2023).
rectum cancer (1 paper, 2024). "Based on the TCGA database, we found the methylation levels of SLC10A3 did not significantly change in colon and rectum cancer tissues than that in the corresponding normal tissues." (PMID 38178258, 2024).
renal carcinoma (1 paper, 2023). A carcinoma arising from the epithelium of the renal parenchyma or the renal pelvis. "While SLC10A3 is down-regulated in renal cancer, uterine corpus endometrial carcinoma and thyroid carcinoma." (PMID 37166424, 2023).
tumor (5 papers, 2023 to 2026). "Single-cell analysis showed SLC10A3 enrichment in tumor-associated astrocytes and macrophages, with enhanced astrocyte-macrophage crosstalk through MIF, MDK, and extracellular matrix remodeling pathways." (PMID 42211491, 2026). "Using IHC scores (cut-off = 7), we divided the specimens into high and low expression groups, with a higher proportion of high SLC10A3 expression in tumor tissues." (PMID 38178258, 2024). "Firstly, we compared the transcriptional levels of SLC10A3 in pan-cancer between tumor and normal samples by applying the TCGA databases." (PMID 38178258, 2024). "Based on the TCGA database, we conducted SLC10A3 single gene analysis, divided the tumor samples into SLC10A3 low expression group and SLC10A3 high expression group by R (version 4.1.1), and screened differentially expressed genes in volcano plot." (PMID 38178258, 2024). "Tissue microarray of CRC confirmed the high expression of SLC10A3 in tumor tissues, which was indicative of poor prognosis, including OS (p-value = 0.022, HR = 2.23(1.16–4.29) and DFS (p-value = 0.026, HR = 2.24(1.10–4.56))." (PMID 38178258, 2024). "We noticed that the predictive capacity of SLC10A3 was the highest among recurrent tumor population, most likely to the fact that they exhibited the higher expression of SLC10A3, and up-regulation of SLC10A3 correlating well with the immune check points." (PMID 37166424, 2023). "The predictive capacity of SLC10A3 was 0.505 in the whole cohort, 0.507 in the primary tumor cohort and 0.674 in the recurrent tumor cohort." (PMID 37166424, 2023). "Hence, systematically illustrating role of SLC10A3 in the tumor immune microenvironment is conducive to identify a novel therapeutic target for LGGs." (PMID 37166424, 2023). "This study comprehensively analyzed SLC10A3 in CRC, evaluating its prognostic significance and influence on the tumor's immune microenvironment." (PMID 38178258, 2024). "We noticed that number of SLC10A3 positive cells is more in LGG tissues than normal tissues in total area and tumor area, and SLC10A3 average cell intensity was stronger in LGG tissues than normal tissues in stroma area." (PMID 37166424, 2023). "In addition, all urinary proteins, except for four (TMEM132A, HLA-DRB1, SLC10A3, RNF150), have been reported as candidate biomarkers for thirty-five neoplastic diseases." (PMID 36918772, 2023). "Our analysis indicated that the level of SLC10A3 is correlated with CRC malignancy in tumor relapse and metastasis, but not in lymph node invasion status and tumor stage." (PMID 38178258, 2024).
cancer (3 papers, 2022 to 2024). A tumor composed of atypical neoplastic, often pleomorphic cells that invade other tissues. "Recent studies have highlighted the pivotal role of SLC10A3 in various cancers, with its mutation being implicated in malignant growth and cancer development." (PMID 38178258, 2024). "In TCGA data, differential SLC10A3 expression was significant among 16 of the 33 cancer types analyzed, including 12 upregulation and 4 downregulation." (PMID 38178258, 2024). "To explore the biological function of SLC10A3 in pan-cancer, especially CRC, we performed a series of bioinformatics analyses." (PMID 38178258, 2024). "We initially mined TIMER database to investigate the expression of SLC10A3 transcription in pan-cancer and LGGs." (PMID 37166424, 2023). "In line with the results from TIMER, we still observed that SLC10A3 expression was up-regulated in most malignant tumors, including LGGs." (PMID 37166424, 2023). "KEGG pathways revealed that SLC10A3 was most likely involved in cytokine-cytokine receptor interaction, viral protein interaction with cytokine and cytokine receptor and transcriptional misregulation in cancer." (PMID 37166424, 2023). "In the TCGA pan-cancer cohort, IRAK1 expression positively correlated with DKC1 (R = 0.54), FAM58A (R = 0.51), NAA10 (R = 0.54), SLC10A3 (R = 0.55), and UBLA4 (R = 0.62)." (PMID 35669566, 2022). "We identified the top five related genes (DKC1, FAM58A, NAA10, SLC10A3, UBL4A) that mostly correlated with IRAK1 by GEPIA2.0; the heatmap displayed the correlation in pan-cancers." (PMID 35669566, 2022).
SLC10A3 also shares sentences with these, for which no sentence is quoted: infection (3 papers); astrocytoma (1); cholangiocarcinoma (1); esophageal carcinoma (1); gastric cancer (1); glioblastoma (1); head and neck squamous cell carcinoma (1); hepatocellular carcinoma (1); lung carcinoma (1); thyroid carcinoma (1); uterine corpus endometrial carcinoma (1).